TLR4 (toll like receptor 4)
Diseases named in the same sentence as TLR4 in open-access papers (continued):
Sharing a sentence is not in itself a finding about the gene and the disease.
endotoxemia (continued). "Sennoside A reduced endotoxemia and TLR4 protein expressions in db/db mice compared with those of control ones." (PMID 32685087, 2020). "Treatment with berberine increased the survival rate of mice with LPS-induced endotoxemia, and this effect was due to its high affinity for the TLR4/ MD-2 receptor with the pro-inflammatory cascade block." (PMID 33137930, 2020). "HFD-induced endotoxemia was accompanied by a marked Tlr-4 gene upregulation, enhanced NF-κB (also known as Rela) transactivation and subsequent inflammation in both liver and gut." (PMID 30971408, 2019). "Our findings raises important questions about the impact of maternal obesity and endotoxemia to fetal hematopoiesis, as fetal immune precursors are also sensitive to TLR4 signals." (PMID 29453396, 2018). "It should be noted that expression of the receptor TLR4, which specifically binds LPS and is an important marker of the inflammatory response, was also increased during the stage of endotoxemia studied, indicating hyperinflammation." (PMID 29795607, 2018). "In this way, we aimed to distinguish between TLR4-dependent and TLR4–independent dynamic programs of systemic and organ specific inflammation induced by endotoxemia." (PMID 30399158, 2018). "We also confirmed and extended many findings regarding the effects of LPS and the role of TLR4 demonstrated previously separately in various organs in the context of experimental endotoxemia in mice." (PMID 30399158, 2018). "Our work also demonstrates that targeting eIF2-α phosphorylation represents a novel pharmacological option to interfere with endotoxemia both by reducing liver damage and altering TLR4-dependent cytokine release." (PMID 28659918, 2017). "We, therefore, subjected OGN WT and KO mice to endotoxemia, a model of septic shock where TLR4 activation is, in part, driving pathogenesis." (PMID 27878326, 2017). "Alleviation of endotoxemia was further supported by the decreased expression of TLR4 and its downstream signaling protein Myd88 in the liver after FMT intervention." (PMID 28484247, 2017). "Although mechanisms underlying endotoxemia induced acute neuro-inflammation are complex and controversial, recent studies have proven that TLR4 signal pathway is in participation with endotoxemia related cognitive dysfunction." (PMID 28059131, 2017). "This activity was demonstrated in vitro using both RAW 264.7 cells and a human Toll-like receptor 4 (TLR4) reporter cell line, as well as in a murine model of endotoxemia using purified LPS for challenge." (PMID 28874372, 2017). "A new humanized antibody against the antigen has been shown to inhibit endotoxin-mediated Toll-like receptor 4 (TLR4) activation better than polymyxin B in vitro, as well as improve survival in endotoxemia-susceptible mice." (PMID 28989972, 2017). "It further demonstrates that Chtx, which inhibits LPS-mediated endotoxemia by competitive binding through TLR4, protects mice against APAP-induced inflammation and mortality." (PMID 27171266, 2016). "We have shown previously that chitohexaose, a small molecule of nematode origin, mediates TLR4-dependent M2 activation of macrophages with prominent IL-10 production and blocks LPS-mediated endotoxemia." (PMID 27125280, 2016). "Rhodostomin (Rn), a snake venom disintegrin, was previously reported to interact with the αVβ3 integrin and the TLR4 on phagocyte in attenuating LPS-induced endotoxemia." (PMID 26987407, 2016). "Similar results were obtained in endotoxemia: the TLR4-positive CD34+ CD38− cells and the fluorescence intensity increased by 63 % and 46 %, respectively." (PMID 26272069, 2015). "Previous in vivo studies that implicated TLR4 in S100A8 and S100A8/A9 mediated inflammation have done so largely in the context of endotoxemia, where TLR4 would be readily activated." (PMID 25706559, 2015).
endotoxemia (continued). "In summary, our results have demonstrated that AnxA2 molecules interact with a TRAM-TRIF adaptor complex and subsequently regulate TLR4 endosomal signaling and its anti-inflammatory action during endotoxemia." (PMID 26527544, 2015). "During endotoxemia, LPS is detected by Toll-like receptor 4 (TLR4) on sentinel cell (endothelium, Küpffer cells, etc.)that initiates the subsequent inflammatory response, including neutrophil recruitment to the liver." (PMID 26457108, 2015). "Our results indicate that WEGL supplementation improves gut barrier integrity, reduces endotoxemia, decreases TLR4 signalling and decreases inflammation in obese mice fed with a HFD." (PMID 26102296, 2015). "We examined the effects of WEGL on LPS serum levels (that is, endotoxemia) and TLR4 protein expression in hepatic and adipose tissues." (PMID 26102296, 2015). "Since we showed Neu1 to be a key regulator of Siglec-E-TLR4 interaction and of the TLR4 function in vitro, we sought a genetic model to definitively address the potential role of Neu1 in the host response to endotoxemia." (PMID 25187624, 2014). "In microglia, berberine suppresses neuroinflammatory responses and attenuates the production of inflammatory mediators through suppression of toll-like receptor 4 (TLR4)-nuclear factor-κB (NF-κB) signaling in animal models of endotoxemia." (PMID 25546475, 2014). "Through a series of confirmatory studies, we established that our lead compound C34 inhibits TLR4 in vitro in macrophages and enterocytes, and in vivo in experimental models of endotoxemia and NEC." (PMID 23776545, 2013). "We aimed to investigate the role of TLR4 in the regulation of the hepatic inflammatory reaction during endotoxemia." (PMID 23977376, 2013). "Our lead compound, C34, is a 2-acetamidopyranoside (MW 389) with the formula C17H27NO9, which inhibited TLR4 in enterocytes and macrophages in vitro, and reduced systemic inflammation in mouse models of endotoxemia and necrotizing enterocolitis." (PMID 23776545, 2013). "The aim of this study was to investigate in the pancreatic acinar cells isolated from adult animals, the effects of foregoing infant rats endotoxemia on TLR4, HSP60 and pro-apoptotic Bax, caspase-9 and -3 or antiapoptotic Bcl-2 protein expression." (PMID 22685683, 2012). "The role of platelet-derived TLR-4 as a mediator of microvascular thrombosis in endotoxemia was unrelated to changes in platelet aggregation." (PMID 22911769, 2012). "Platelet-derived TLR-4 has been suggested to mediate various inflammatory responses in endotoxemia, including production of tumor necrosis factor alpha (TNF-α) and interleukin-1 beta (IL-1β), two cytokines reported to enhance microvascular thrombosis." (PMID 22911769, 2012). "Endotoxemia promoted the induction of HSP60 via TLR4 in the infant rats and participated in the LPS-dependent pancreatic tissue protection against acute damage." (PMID 22685683, 2012). "The primary finding of this study was that platelet-derived TLR-4 was sufficient to mediate enhanced microvascular thrombosis in endotoxemia." (PMID 22911769, 2012). "Both RAGE and TLR4 are widely expressed in the lung tissue, so this pathway is of major relevance during the alveolar inflammatory response after endotoxemia." (PMID 22768176, 2012). "Treatment of acini with caerulein resulted in the dose-dependent increase of TLR4 protein level in the rats subjected to endotoxemia in the suckling period of life." (PMID 22685683, 2012). "Endotoxemia dose-dependently increased TLR4, Bax, HSP60, and both caspases protein signals in the pancreatic acini, further inhibiting antiapoptotic Bcl-2." (PMID 22685683, 2012). "This dissociation between the pro-thrombotic and systemic pro-inflammatory cytokine responses in endotoxemia provides new insight into the role of platelet-derived TLR-4." (PMID 22911769, 2012).
endotoxemia (continued). "Since we studied the potential anti-inflammatory roles of MFG-E8 by utilizing the LPS induced murine model of endotoxemia, we therefore highlighted the features of TLR4-mediated innate immune responses upon rmMFG-E8 pre-treatment." (PMID 22114683, 2011). "The resulting endotoxemia would then activate TLR4 mediated signaling and culminate in the release of pro-inflammatory cytokines." (PMID 20221393, 2010). "In conclusion, there is clear evidence that alcohol consumption leads to increased intestinal permeability and endotoxemia, which results in activation of innate immunity via TLR4 signaling." (PMID 20827314, 2010). "Cardiometabolic comorbidities promote gut dysbiosis, loss of short-chain fatty acid (SCFA)-producing taxa, and disruption of the intestinal barrier, leading to endotoxemia and upregulation of pro-inflammatory pathways such as TLR4- and NLRP3-mediated signaling." (PMID 41599934, 2026). "In conclusion, our findings indicate that isaridin E exerts robust anti-inflammatory effects in LPS-induced endotoxemia through the suppression of the TLR4/NF-κB signaling axis, positioning it as a promising therapeutic candidate for vascular inflammatory disorders." (PMID 40278266, 2025). "However, most studies focus on evaluating LPS/TLR4 signaling in inflammatory responses and reactive oxygen species (ROS) production, thus subsequently regulating myocardial function during endotoxemia." (PMID 40649741, 2025). "Increased gram-negative bacteria, such as Klebsiella oxytoca, promote endotoxemia, triggering inflammation via TLR-4, damaging podocytes, and causing albuminuria." (PMID 39941397, 2025). "TLR4 expression is enhanced in the thymus of Swiss albino mice with experimental endotoxemia." (PMID 40564264, 2025). "In the conclusion, we provide specific suggestions on how to upregulate LPS clearance to control TLR4-mediated inflammation, offering valuable strategies that could lead to novel therapeutic approaches for managing endotoxemia." (PMID 39329771, 2024). "During the development of endotoxemia, LPSs bind to toll-like receptor 4 (TLR4) and increase the concentration of inflammatory markers such as IL-1α, IL-6, INF-γ, and TNF-α, and consequently systemic chronic intestinal inflammation may develop." (PMID 39193369, 2024). "TLR4 was also demonstrated to be a master regulator of the muscle wasting induced by endotoxemia." (PMID 38338123, 2024). "Elevated levels of LPS can trigger immune responses by interacting with the host mucosal surface cells through the Toll-like Receptor 4 (TLR4) and nucleotide oligomerization domain-containing receptors, thus contributing to a state of endotoxemia and systemic inflammation." (PMID 38399558, 2024). "LPS is a major component of the cell wall of gram-negative bacteria and activates toll-like receptor 4 on the surface of macrophages to secrete pro-inflammatory cytokines upon entry into the bloodstream, causing endotoxemia." (PMID 37689643, 2023). "TLR4 is the principal receptor that recognizes the lipopolysaccharide of the outer cell wall of gram-negative bacteria, and knockdown of the TLR4 gene helps to defend against endotoxemia." (PMID 36032662, 2022). "Finally, the effects of QRQZ on gut mucosal permeability, endotoxemia, and liver TLR4/NF-κB signaling pathway levels were examined." (PMID 36743916, 2022). "Previous studies showed that quercetin could reverse gut microbiota imbalance and related endotoxemia-mediated toll-like receptor 4 (TLR-4) pathway induction." (PMID 34836315, 2021). "Thus, the activation of platelet TLR4 by LPS was reported to be responsible for the copious inflammatory factor release and reduced platelet counts (at least in a mouse model of endotoxemia)." (PMID 34360659, 2021). "Therefore, LPS-mediated endotoxemia affects brain inflammation by enhancing the passage of circulating inflammatory cytokines across the blood–brain barrier, stimulating microglia via TLR4, and/or inhibiting vagal afferent neurons." (PMID 35056501, 2021).
endotoxemia (continued). "Endotoxemia in small intestinal bacterial overgrowth (SIBO) patients likely activate the toll-like receptor 4 (TLR-4) and cluster of differentiation 14 (CD14) receptor by stimulating the expression of nuclear factor-κB (NF-κB) that mediates the production of proinflammatory cytokines." (PMID 32731496, 2020). "Collectively, our results indicate that pharmacological inhibition of TLR4 signalling may be a novel therapeutic intervention for endotoxemia-induced muscle wasting." (PMID 31959927, 2020). "These components may facilitate potent activation of innate immunity when triggered by low-grade endotoxemia, as demonstrated by the lipid-A molecule’s interaction with the toll-like receptor 4 (TLR4), mediating expression of pro-inflammatory cytokines." (PMID 32599766, 2020). "However, despite the differences in the initiation of these inflammatory models, both LPS-induced endotoxemia and carrageenan-induced peritonitis proceed via TLR4 activation." (PMID 33114200, 2020). "Our group was the first to report that the GWI mouse model exhibited significant alteration of the gut microbiome, leading to gut leaching, increased endotoxemia, and Toll-like receptor 4 (TLR4) activation which established a mechanistic connection between gastrointestinal and neuroinflammation." (PMID 32784362, 2020). "We speculate that our observation that endotoxemia downregulates factors for Se processing may have implications for restoring Se homeostasis during clinical states that activate TLR4 signaling." (PMID 33224150, 2020). "The LPS is directly responsible for endotoxemia, so-called, “low grade inflammation”, via Toll-like receptor-4 (TLR-4), by inducing the production of IL-1β, TNF-α and IL-6 from macrophages and, at the same time, some of the adipocytes are also differentiated into “macrophage-like” cells." (PMID 32650509, 2020). "Although certain types of cancer that cause gut barrier dysfunction can lead to endotoxemia, resulting in systemic activation of TLR4, endotoxemia is not a common feature of cancer." (PMID 31480237, 2019). "It was speculated that overexpression of TLR4 was involved in the occurrence and development of intestinal mucosal injury and endotoxemia in mice with OJ." (PMID 31671112, 2019). "During endotoxemia, LPS-induced toll-like receptor-4 (TLR-4) activation promotes expressions of inflammatory cytokines including tumor necrosis factor-α (TNF-α), interleukins (IL-1β and IL-6) through transcription of nuclear factor-κB (NF-κB), which is a crucial regulator of immune system." (PMID 28852469, 2017). "To explore whether B. quintana LPS can be used for in vivo studies to neutralize TLR4, we administered B. quintana LPS in an endotoxemia model." (PMID 27670746, 2016). "Therefore, besides induction HSP70, direct inhibition of HSP90 by 17-DMAG, resulting in suppression of TLR4 expression, NF-κB activation, and iNOS activity, contributes to the beneficial effect on MODS caused by endotoxemia." (PMID 27224288, 2016). "Thus, this 43% reduction in plasma IL-1β detected during LPS-induced endotoxemia—attributable to a loss of C5aR1 signaling—strongly suggested that C5a engages C5aR1 in vivo to amplify TLR4-mediated IL-1β production in the endotoxemia model." (PMID 27382187, 2016). "WEGL reduced endotoxemia and TLR4 protein expression in HFD-fed mice compared with HFD alone." (PMID 26102296, 2015). "It was found that dexmedetomidine at the doses of 10 and 20 μg/kg decreased CLP-induced pulmonary inflammation and mortality, reduced production of IL-6 and TNF-α in plasma and BALF of septic rats, and suppressed TLR4/MyD88 expression and NF-κB activation in lung of endotoxemia rats induced by CLP." (PMID 23690665, 2013). "Experimental endotoxemia, which stimulates toll-like receptor 4 (TLR-4) signaling in vivo, may be an informative model to study cardio-metabolic traits in humans." (PMID 22709547, 2012).
endotoxemia (continued). "Thus, it is conceivable that platelet-derived microparticles mediate platelet TLR-4-induced pro-thrombotic responses in endotoxemia." (PMID 22911769, 2012). "Thus Chtx appears to protect against endotoxemia by two mechanisms - a) it competitively inhibits LPS induced activation by binding to TLR4 and/or b) it activates macrophages by alternate anti-inflammatory pathway." (PMID 22654663, 2012). "Endotoxemia in the newborn rats induced by increasing doses of LPS (5, 10 or 15 mg/kg/day × 5 days) resulted in significant and dose-dependent increase of TLR4 protein level in the acini incubated with caerulein (10−8 M) as compared to the group subjected to caerulein alone." (PMID 22685683, 2012). "However, platelet-derived TLR-4 has been reported to mediate functional responses in endotoxemia, including platelet sequestration, thrombin generation, and both enhanced and decreased activation of isolated platelets." (PMID 22911769, 2012). "Impaired intestinal barrier function promoted by JNK during H/R may therefore also lead to portal vein endotoxemia, activation of TLR4 with phosphorylation of MAPKs, and increased production of inflammatory cytokines and ROS by hepatic Kupffer cells." (PMID 22791932, 2012). "Moreover, both alcohol and MASLD disrupt intestinal barrier integrity, leading to endotoxemia and bacterial translocation—key drivers of hepatic inflammation through Toll-like receptor 4 (TLR4) activation and transformation of hepatic stellate cells into myofibroblastic phenotypes." (PMID 40647333, 2025). "Consequently, metabolic endotoxemia—persistently elevated circulating LPS levels—activates Toll-like receptor-4 (TLR4), an immune receptor that recognizes endotoxins, triggering NF-κB inflammation, signaling, and downstream inflammatory cascades, fostering systemic insulin resistance." (PMID 40871736, 2025). "In addition, the presence of (1→3)-β-D-glucan (BG), a major component of Candida cell wall, in serum (from gut translocation) worsens the endotoxemia-induced inflammation, partly through the synergy between Toll-like receptor 4 (TLR-4) and Dectin-1, the receptors of LPS and BG, respectively." (PMID 34068595, 2021). "Notably, the intestinal hyper-permeability was associated with portal endotoxemia and increased hepatic/MAT/intestinal macrophage infiltration, inflammation and corresponding cytokines levels (IL-6, MCP-1, F4/80, TNFα, NFκBp65, TNFRI and TLR4) in NASH-V rats." (PMID 29684027, 2018). "However, it warrants further studies to demonstrate whether the production and release of TNF-α, IL-1βand IL-6 is altered in HMGB1/TLR4 signaling pathway and whether this is the main pathological mechanism in endotoxemia induced acute neuro-inflammation." (PMID 28059131, 2017). "Thus, based on the changes in hippocampus 5-HT level, we wondered whether classic HMGB-1/TLR4 related inflammation pathway participates in the pathological process of endotoxemia induced acute neuro-inflammation." (PMID 28059131, 2017). "The translocated LPS are detected by CD14 and toll-like receptor 4 (TLR4), which causes the release of pro-inflammatory cytokines such as tumor necrosis factor alpha (TNFα), interferon alpha (IFNα), interferon-gamma (INFγ) and interleukins (IL1β or IL6), which can eventually result in endotoxemia." (PMID 27924137, 2016). "We expect that this humanized anti-TLR4 antibody may have applications in endotoxemia therapy." (PMID 26512658, 2015). "Thus, blocking TLR-4 or administering IL-6 or IL-10 might impart protection against endotoxemia in the clinical field." (PMID 25759837, 2015). "Collectively, these data position intestinal barrier integrity as a proximal node linking fermented-food matrices to reduced endotoxemia (LPS/LBP), dampened hepatic TLR4–MyD88–NF-κB signaling, and improved insulin sensitivity." (PMID 41599407, 2026). "In endotoxemia, PHLDA1 inhibits pro-inflammatory responses by repressing the TLR4/MyD88/NF-κB pathway through TOLLIP." (PMID 39735680, 2025).